ATF2 (activating transcription factor 2)
Diseases named in the same sentence as ATF2 in open-access papers (continued):
Sharing a sentence is not in itself a finding about the gene and the disease.
tumor (continued). "The growth rate and weight of implanted tumours in the Agomir + ATF2 group were significantly higher than those in the AgomiR + Vector group." (PMID 32014006, 2020). "As type I interferon signaling in cancer is a potent inducer of anti-tumor immune surveillance, our findings are consistent with a role for ATF2-mediated suppression of IFNβ in the T cell exclusion phenotype." (PMID 32117236, 2020). "A xenograft tumor model was established to validate the role of ATF2/NEAT1 axis in LUAD progression in vivo." (PMID 33298086, 2020). "GDNF, also called ATF or ATF2, is a well-characterized oncogene that promotes tumor growth, invasion, and metastasis, in addition to tumor microenvironment alterations." (PMID 32102656, 2020). "Through targeting ATF2, tumor suppressor miR-204 can inhibit cell proliferation and migration, and promote G1 arrest and cell apoptosis in NSCLC." (PMID 31885751, 2019). "AP-1 transcription factor complexes formed by the members of the JUN and ATF family such as JUN:ATF2 are also seen to play a role in tumor formation." (PMID 30563222, 2018). "For its key role in regulating radiosensitivity of tumor cells, ATF2 was selected as the potential target of miR-144-5p in present study." (PMID 29850528, 2018). "In the removed tumor tissues, cisplatin treatment induced obvious phosphorylation of ATF2 in control Hep-2/R cells." (PMID 29108284, 2017). "We have previously shown that SS18-SSX interacts with its partners at promoters recognized by ATF2, repressing transcription at critical tumor suppressor loci including EGR1 and CDKN2A." (PMID 28056055, 2017). "Within ER+ tumours, most of the associations observed in the whole series remained significant including nuclear p-ERK1/2, p-p38 and p-ATF2." (PMID 27592113, 2016). "Cytoplasmic accumulation of ATF-2 was found to sensitize tumor cells to standard-of-care HNSCC treatments, such as cisplatin and radiation." (PMID 27764820, 2016). "In a promotable skin cell model, the nuclear levels of ATF2 were increased during tumor promotion, whereas this increase was inhibited by shikonin." (PMID 25961580, 2015). "Tumor xenografts of B16F10 cells stably transfected with ATF2 shRNA exhibited a higher tumorigenic compared to the empty vector control." (PMID 25852302, 2015). "In fact, the mice that displayed an increased growth of B16F10 cells also showed a lower expression of ATF2 in the tumor tissue." (PMID 25852302, 2015). "Depending on its subcellular localization, ATF2 can elicit divergent functions of oncogenic or tumor suppressor activities." (PMID 26462148, 2015). "Activating transcriptional factor (ATF2) was identified as a tumor suppressor in mouse skin keratinocytes and Pcyt2 was down-regulated in the ATF2 null mice, a mouse skin carcinogenesis model." (PMID 23354482, 2013). "When subjected to a two-stage DMBA/TPA skin carcinogenesis protocol, mice expressing the inactive ATF2 display increased tumor formation, and keratinocytes derived from these mice display enhanced anchorage-independent growth." (PMID 23762562, 2013). "IHC showed that the CDDP treatment increased p-c-Jun, p-ATF2 and Galectin-1 in tumor tissues." (PMID 37215991, 2023). "However, ATF2 was also reported to serve as a tumor suppressor by suppressing the cancer driver TROP2 in CRC40." (PMID 37816820, 2023). "In addition, resveratrol (3,5,4’-trihydroxystilbene), a naturally occurring polyphenol with antioxidant activity, reportedly increases the transcriptional activation potentials of CREB and ATF2 to mediate cytoprotective and tumor suppressive outcomes." (PMID 36765266, 2023). "These contradictory roles of ATF2 may indicate that it has dual roles depending on the type of tumor and other factors affecting the tumor." (PMID 37955015, 2023).
tumor (continued). "Inhibition of p38 MAPK phosphorylation might influence more downstream targets in addition to ATF2 and can be effective to induce significant tumor cell apoptosis at therapeutically relevant levels." (PMID 38137525, 2023). "Interestingly, a high number of ATF2-p-ATRThr1989 foci were also present in the cytoplasm of the 5-FU-treated tumor cells." (PMID 37237279, 2023). "Furthermore, these ATF2 mutant animals had an increased frequency of spontaneous and chemically driven tumor formation, indicating the relevance of ATF2 phosphorylation by ATM in the acute cellular response to DNA damage and genomic stability maintenance." (PMID 37955015, 2023). "Finally, our data demonstrate that ATF2 acts as a tumor suppressor by inhibiting the cancer driver TROP2." (PMID 35838828, 2022). "We suggest that the presence of an ATF2-negative tumor cell population is associated with a higher de-adhesion, migration, and invasion potential of tumors." (PMID 35838828, 2022). "In this study, using CRISPR/Cas9-mediated ATF2-KO cells, they discovered that ATF2 acts as a tumor suppressor by inhibiting the cancer driver trophoblast cell surface antigen 2 (TROP2), which is associated with cell de-adhesion and cell migration without triggering EMT." (PMID 36497228, 2022). "Previous studies have shown the role of miR-299-5p/ATF2 axis in immune escape of tumor cells." (PMID 35784175, 2022). "In this scenario, co-upregulation of MAPK14 (together with ATF2) might enable the competitive edge for MAPK14- as compared to ATM-mediated ATF2 activation, thereby driving tumor progression and drug resistance." (PMID 33803354, 2021). "Upon phosphorylation by MAPK14, ATF2 can function as a tumor promotor." (PMID 33803354, 2021). "Furthermore, we used IHC to analyze the protein expression level of ATF2 in tumor tissues in both the knockdown TTN-AS1 and control groups." (PMID 34671381, 2021). "And the transcription level of ATF2 in HCC tumor sample was higher than the normal tissues." (PMID 34273954, 2021). "Moreover, blocking the AP1 transcription complex (Jun, Fos, Maf and ATF2 protein subfamilies) leads to increased tumour sensitivity to endocrine therapy and delayed onset of resistance through the inhibition of both proliferative and survival signals." (PMID 33198803, 2020). "That work suggested a tumour-suppressive role of ATF2 in ER-positive breast cancer." (PMID 33198803, 2020). "Moreover, cancer-derived exosomes produce activating transcription factor 2 (ATF2), metastasis-associated protein 1(MTA1), and CD147, all angiogenic factors, in response to the hypoxic noxa given by tumor growth, and the associated increased metabolic demand." (PMID 33228245, 2020). "Interestingly, a recent study showed that JNK can suppress tumor formation via ATF2-dependent gene expression and that ATF2-dependent gene expression is frequently downregulated in human cancers." (PMID 31766464, 2019). "In addition, restoration of ATF2 significantly inhibited miR-144-mediated suppression of the tumor volume and weight in A549 cell xenograft mice exposed to IR." (PMID 29850528, 2018). "We suggest that targeting chromatin-bound activated Chk1, as well as GCN5, PCAF, p300/CBP, c-Jun, and ATF2, might be a novel potential molecular therapy for the prevention of UC-related tumour progression." (PMID 28751935, 2017). "Previous studies have suggested a role for ATF-2 in oncogenic and tumor-suppressor functions." (PMID 27764820, 2016).
tumor (continued). "Tumor volume and weight were reduced in ATF2 shRNA group compared to control group." (PMID 27377902, 2016). "Thus, the present data demonstrates that miR-204 regulates ATF2 expression, and thus over-expressed miR-204 functions as a tumor suppressor in GBM progression." (PMID 27588402, 2016). "Meanwhile, ATF2 also has been reported to regulate the tumor behaviors." (PMID 27588402, 2016). "In other tumors, tumor suppressor activity of cytosolic ATF2 has also been observed." (PMID 26462148, 2015). "However, ATF2 also exerts tumor suppressive activity in chemically induced skin carcinogenesis model, and protein kinase-c ε (PKCε) shifts ATF2 towards to tumor promotion." (PMID 25961580, 2015). "Tumor-targeted ATF2 modulators may be useful as sensitizers in the treatment of ATF2-overexpressing tumors." (PMID 24403257, 2013). "Thus, this cooperation between TCF1/LEF1 and ATF2 represents an unexpected new strategy used by tumor cells to aberrantly activate TCF1/LEF1 signaling independently of β-catenin and the Wnt canonical pathway." (PMID 23966864, 2013). "Proteomic profiles revealed that the constituents of high-grade OC-derived exosomes, such as activating transcription factor 2 (ATF2) and metastasis-associated protein 1 (MTA1), among others, had a profound impact on angiogenesis and may play a key role in enhancing tumor development." (PMID 28506269, 2017). "Notably, ATF2 expression was even higher in tumor thrombus than primary tumors." (PMID 27377902, 2016). "Rigosertib-dependent translocation of p-ATF-2 occurred in HNSCC independent of HPV status, but did not occur in Normal Human Dermal Microvascular Endothelial Cells (HMVEC-d), suggesting that rigosertib-induced translocation of ATF-2 may be specific to tumor cells." (PMID 27764820, 2016). "Hence, we believe that the ATF2 may be more important in promoting tumor growth in this model, and it can be speculated that ATF2 might initially contribute to the events towards tumor proliferation." (PMID 25852302, 2015). "For A2AR, the agonist HENECA influences the immune response within the tumor microenvironment by increasing AC level and intracellular cAMP and suppressing p38 MAPK and activating transcription factor-2 (ATF-2) phosphorylation." (PMID 41573544, 2025). "It has been reported to act as a tumor suppressor in HCC, increasing sorafenib sensitivity through the downregulation of MAPK13 and modulating the MEK/ERK and ATF2 signaling pathways." (PMID 39906666, 2024). "Correlation analysis displayed that the metastatic rates of the tumor cells were positively correlated with the expression of ANKRD49, MMP-2, MMP-9, p-JNK, p-c-Jun or p-ATF2." (PMID 37964204, 2023). "Specifically, proteins like ATF2, MTA1, ROCK1/2, and CD147 are involved in tumor angiogenesis, while GNA12, EPHA2, and COIA1 promote migration and metastasis." (PMID 38132461, 2023). "MiR-451 inhibits NSCLC tumor cell growth and migration by targeting LKB1/AMPK and ATF2 and sensitizes NSCLC cells to cisplatin by regulating Mcl-1." (PMID 37190222, 2023). "Activating transcription factor-2 (ATF2) is a member of the basic leucine zipper family of DNA-binding proteins, which exhibits both oncogenic and tumor suppression activity in different tumors." (PMID 35641966, 2022). "TROP2 silencing under de-adhesive conditions in HCT116 and their ATF2-KO cells led to significantly larger cell aggregates, suggesting a role for TROP2 in tumor cell adhesion." (PMID 35838828, 2022). "The monoclonal expansion approach of CRISPR/Cas9-mediated ATF2-KO cells allowed us to abrogate ITH and capture, at least partly, the genetic diversity in the tumor, leading to the identification of a novel regulatory axis between ATF2 and TROP2." (PMID 35838828, 2022). "According to reports, ATF2 not only promotes tumor cell metastasis and maintains the characteristics of tumor stem cells through the JNK/ATF2 signaling pathway, but also serves as an early response gene to stress and DNA damage." (PMID 34715922, 2021).
tumor (continued). "Our findings thus demonstrate that miR-216a-3p enhances sorafenib sensitivity in HCC cells and tumor tissues by decreasing MAPK14 levels, thereby inhibiting the MAPK14-dependent MEK/ERK and ATF2 signaling." (PMID 33021963, 2020). "Activated ATF-2 binds to the AP1 complex to regulate diverse cellular functions and can either act in tumor promotion or tumor suppression depending on its sub-cellular localization." (PMID 27764820, 2016). "Mitochondrial accumulation was induced in the mouse tumor cell line B16F10 as early as 4 hours after paclitaxel (PTX) treatment, whereas leptomycin B (LMB), the nuclear export inhibitor, prevented the ATF2 mitochondrial localization." (PMID 25852302, 2015). "We also demonstrate that silencing of ATF2 in B16F10 cells increases both the incidence and prevalence of tumor xenografts in vivo, whereas stably mitochondrial ATF2 transfection inhibited B16F10 tumor xenografts growth." (PMID 25852302, 2015). "It was found that it regulated cellular responses along with apoptotic mechanisms in cells without developing resistance in suppressing tumor growth by making changes on Atf2, Casp8, Bcl2 and Irf5 genes and proteins." (PMID 41656578, 2026). "Additionally, exosomal proteins like ATF2, MTA1, and CD147 have been shown to induce tumor angiogenesis under hypoxic conditions." (PMID 38132461, 2023). "CTCF, FOS, ATF2, and YY1 in H3F3B+ tumor cells were found to regulate angiogenesis." (PMID 37430270, 2023). "According to a previous study, IL8 is involved in transcriptional regulation by activated NFκB,47 activating transcription factor 2 (ATF2), JUN, MAPK48 and other transcription factors; these transcription factors have also been reported to regulate tumour angiogenesis." (PMID 35224833, 2022). "M1 macrophage-derived exosomal lncRNA-HOTTIP and M2 macrophage-derived exosomal lncRNA-AFAP1-AS1 affect tumor metastasis by modulating the miR-26a/ATF2 axis and miR-19a/b-3p/TLR5/NF-κB signaling pathway, respectively, which provides a potential strategy for tumor immunotherapy." (PMID 36601121, 2022). "In contrast, HCT116 ATF2-KO clones displayed more loosely arranged tumor masses lacking a clear pushing front." (PMID 35838828, 2022). "Based on results, LINC00882 may be a tumor promotor for HCC, and ATF2 could activate its transcription." (PMID 34513693, 2021). "ATX secreted from tumor and stromal cells induces LPA, which enhances NF-κB expression via the PKC or AKT pathway, induces ATF-2 via the Rho-CDC42-p38 MAPK pathway, and activates STAT3 and STAT5, which induces the synthesis of inflammatory cytokines, chemokines, and COX-2." (PMID 31035435, 2019). "ATF2 was elevated in RCC tissues with larger tumor size, tumor thrombus or distant metastasis." (PMID 27377902, 2016). "In summary, these results suggest that shikonin, rather than inhibiting PKM2 in vivo, suppresses the ATF2 pathway in skin carcinogenesis." (PMID 25961580, 2015). "Together, our results provide compelling evidence for a new mechanism of constitutive TCF/LEF activation in tumor cells, which is independent of β-catenin and involves cooperation with ATF2 transcription factors." (PMID 23966864, 2013). "Expression of an inactive mutant form of ATF2 (lacking the DNA binding and leucine zipper domains) in the basal epidermis results in reduced tumor formation." (PMID 23762562, 2013). "Likewise, ATF2, CHEK1, DCAF8, and PAX8 showed diverse expression across the different tumor grades." (PMID 36831395, 2023).
tumor (continued). "Therefore, ATF2 could not further exert its tumor suppressive effect on the ATR-Chk1 complex, resulting in drug resistance." (PMID 37237279, 2023). "The gga-miR-15b was downregulated in splenic tumours after MDV infection and had a negative effect on the expression of ATF2, facilitating viral replication by increasing the expression of the ATF2." (PMID 29704894, 2018).